RN7SKP293 (RN7SK pseudogene 293)
Gene: Miscellaneous RNA gene on chromosome 6 (12,406,486 to 12,406,781, reverse strand). Ensembl gene ENSG00000223321.
Homologues: Orthologues: chimpanzee 7SK (98% identical), mouse Gm54918 (48% identical). Paralogues in human: 7SK (77% identical), RN7SKP187 (73% identical), RN7SKP118 (72% identical), RN7SKP178 (72% identical), RN7SKP174 (71% identical), RN7SKP227 (71% identical), RN7SKP185 (71% identical), RN7SKP48 (70% identical), RN7SKP62 (69% identical), RN7SKP76 (69% identical), RN7SKP160 (69% identical), RN7SKP180 (68% identical), and 283 more.